MIR654 (microRNA 654)
Synonyms: hsa-mir-654; MIRN654; mir-654
Gene: MicroRNA gene on chromosome 14 (101,040,219 to 101,040,299, forward strand). Ensembl gene ENSG00000207934.
Gene Ontology:
Biological process: miRNA-mediated post-transcriptional gene silencing
Homologues: Orthologues: chimpanzee ptr-mir-654 (100% identical), macaque mml-mir-654 (100% identical), guinea pig MIR654 (77% identical).